CETP (cholesteryl ester transfer protein)
Diseases named in the same sentence as CETP in open-access papers (continued):
Sharing a sentence is not in itself a finding about the gene and the disease.
diabetes (continued). "Our results suggest that joint genetic inhibition of CETP and SGLT2 leads to decreased glycated hemoglobin and decreased risk of diabetes." (PMID 38962682, 2024). "Taken together, these results constitute genetics-driven evidence suggesting that combination therapy with CETP and SGLT2 inhibitors confers improved protection against hyperglycemia and diabetes risk compared to SGLT2 inhibitors alone." (PMID 37398493, 2023). "Since diabetes is a strong risk factor for ASCVD, the effect of CETP inhibition on diabetes provides an additional mechanism by which CETP inhibitors can reduce ASCVD risk in the longer term." (PMID 34849601, 2022). "On-target CETP inhibition, assessed through Mendelian randomization, is expected to reduce the risk of CHD, heart failure, diabetes, and chronic kidney disease, while increasing the risk of age-related macular degeneration." (PMID 34561430, 2021). "Interestingly, administration of CETP inhibitors could lower diabetes risk." (PMID 32245262, 2020). "Genotype frequency of the CETP TaqIB polymorphism was as follows: 18.9% for B1B1, 61.1% for B1B2 and 20% for B2B2 in patients with diabetes; 13.7% for B1B1, 64.4% for B1B2 and 21.9% for B2B2 in healthy people." (PMID 33123324, 2020). "The presence of the B1B1 Taq1B CETP genotype contributes to the presence of diabetes, independently of age, sex, BMI and waist." (PMID 22073289, 2011). "Indeed, previous meta-analyses of existing randomized controlled clinical trials of CETPi therapies have shown that CETP inhibitors significantly reduce the incidence of new onset diabetes while improving glucose homeostasis and metabolism." (PMID 38962682, 2024). "was linked to the higher levels of CETP activity observed in diabetic patients, Overall, there is no consensus on how diabetes affects the cholesterol efflux capacity of HDL, and we can conclude that not all of HDL functions are modified with HDL oxidation." (PMID 36339401, 2022). "Future research is needed to elucidate the specific mechanisms of the link between CETP inhibition and incident diabetes, including the impact of CETP inhibition on cholesterol efflux from beta-cells, induction of insulin synthesis by beta cells, and increased glucose uptake by muscle." (PMID 35441656, 2022). "The functionality of apoC1 on CETP activity is impaired in diabetes that might account, at least in part, for the increased plasma CETP activity observed in patients with diabetes." (PMID 36471375, 2022). "Beyond the use of apoC1 level as a new marker of diabetes severity, the restoration of apoC1 functionality might help to counteract the deleterious effects of increased CETP activity on plasma lipoprotein profile in this population at high cardiovascular risk." (PMID 36471375, 2022). "This implies either a non-linear relationship between HDL-C changes and diabetes risk, or a pathway between CETP inhibition and diabetes that is independent of HDL-C." (PMID 35441656, 2022). "Therefore, in the current study, we examined the interaction of CETP TaqB1 polymorphism with dietary insulin index and load (DII and DIL), in altering on CVD risk factors among type 2 diabetes mellitus (T2DM)." (PMID 34354158, 2021). "We also apply POINT to the Action to Control Cardiovascular Risk in Diabetes (ACCORD) clinical trial data, finding promising rare variants in PCSK9, ANGPTL4 and CETP that may be associated with lipoprotein-related outcomes." (PMID 30779729, 2019). "Further, whether increased or decreased CETP activity is favorable for the development of diabetes needs to be investigated." (PMID 31597401, 2019). "The key clinically relevant observations are that both acute HDL elevation via short-term reconstituted HDL (rHDL) infusion and chronically raising HDL via a cholesteryl ester transfer protein (CETP) inhibitor reduce blood glucose in individuals with type 2 diabetes mellitus (T2DM)." (PMID 26582989, 2015).
diabetes (continued). "In addition, a recent study in patients with diabetes reported that glycation of ApoC-I reduces its inhibitory effect on CETP." (PMID 25725623, 2015). "High incidence of disease in North Indian population and lack of study exploring the genetic basis of diabetes made us to study the association of CETP TaqI B and D442G; and APOE HhaI polymorphisms with T2DM." (PMID 15992403, 2005). "Furthermore, the lack of interaction effect suggests that genetic CETP or SGLT2 inhibition does not attenuate the effect of the other on glycated hemoglobin or diabetes risk." (PMID 38962682, 2024). "To determine whether joint CETP and SGLT2 inhibition has an impact on diabetes risk within each of our groups, we leverage the same analytical framework as detailed above for glycated hemoglobin but use Cox proportional hazards modelling instead of linear regression." (PMID 38962682, 2024). "Furthermore, joint CETP and SGLT2 inhibition is associated with decreased incidence of diabetes (log-odds ratio) compared to control (Effect size: −0.068; 95% CI: −0.115 to −0.021; p-value: 4.44E-03) and SGLT2 inhibition alone (Effect size: −0.062; 95% CI: −0.112 to −0.012; p-value: 0.0149)." (PMID 37398493, 2023). "Furthermore, the lack of interaction effect suggests that genetic CETP or SGLT2 inhibition doesn’t attenuate the effect of the other on glycated hemoglobin or diabetes risk." (PMID 37398493, 2023). "To determine whether joint CETP and SGLT2 inhibition has an impact on diabetes risk within each of our groups, we leverage the same analytical framework as detailed above for glycated hemoglobin but use logistic regression instead of linear regression because diabetes is a binary phenotype." (PMID 37398493, 2023). "Since CETP increases pre-beta HDL, which promotes cholesterol efflux via ABCAI/GI,44,60 this is an important additional hypothesis for the mechanism whereby CETP inhibition might reduce diabetes risk." (PMID 34849601, 2022). "In addition, apoC1 loses its ability to inhibit CETP in a context of hyperlipidemia and diabetes." (PMID 36471375, 2022). "Few studies also reported diabetes may suppress hepatic CETP in obese." (PMID 26973702, 2016). "However, CETP activity is lower in patients who progress to diabetes." (PMID 26313355, 2015). "Although our study found abnormal lipid profile in diabetes patients and its association with complications like diabetic neuropathy and retinopathy, yet these lipid profile abnormalities did not correlate with CETP TaqI B or APOE HhaI polymorphisms." (PMID 15992403, 2005). "This has been also suggested by our study, which showed a link between peripheral CETP level and that of some pro-inflammatory cytokines, such as IL-8 and MIP-1b, with an emerging key-role in the field of metabolic disease and diabetes." (PMID 33686615, 2021). "Model 3: adjusted for age; sex; diabetes status; use of metformin, sulfonylurea and antihypertensive medication; and LCAT activity (A) or CETP mass (B)." (PMID 30744100, 2019). "In diabetes, decreased insulin sensitivity, low HDL-C, and hypertriglyceridemia result in highly impacted blood levels of cholesteryl ester transfer protein (CETP), which facilitates the transport of cholesterol ester and triacylglycerol between HDL-C and LDL-C particles." (PMID 40314056, 2025). "It is important to note that since CETP and SGLT2 inhibitors are both oral drugs, their combination therapy represents an oral therapeutic strategy for treatment-resistant diabetes prior to use of injectable drugs such as insulin or glucagon-like peptide 1 (GLP1) receptor agonists." (PMID 38962682, 2024). "The authors demonstrated that there were significant benefits of using niacin for MI and coronary revascularization, but this was not the case for CETP inhibitors despite the higher occurrence of diabetes in the treated patients." (PMID 38786974, 2024).
diabetes (continued). "The baseline CETP level, a possible surrogate for hepatic cholesterol accumulation, was an independent positive determinant of pitavastatin-induced changes in LDL-C and sd LDL-C levels in hypercholesterolemic patients with type 2 diabetes mellitus." (PMID 26984517, 2016). "A study on individuals without diabetes reported that insulin infusion did not exert any significant effects on LCAT or CETP activity." (PMID 25725623, 2015). "The association of CETP variants with coronary artery disease (CAD) and type 2 diabetes mellitus (T2DM) has been investigated in several studies without consistent results." (PMID 23157875, 2012). "It is not known, therefore, what the consequences might be of CETP inhibitor monotherapy for the new-onset of diabetes." (PMID 35441656, 2022). "For patients with diabetes, an increase in small triglyceride-rich particles was reported in the HDL composition, in detriment of large and very large particles, an alteration that could be due to an increased CETP (cholesteryl ester transfer protein) activity." (PMID 36553147, 2022). "A conciliatory view of most conflicting clinical and experimental data is that CETP per se is not relevant to glucose homeostasis/insulin sensitivity, but actually the HDL-cholesterol levels and perhaps the HDL functionality is important to regulate glucose metabolism and modulate diabetes risk." (PMID 26758205, 2016). "Model 4: adjusted for age; sex; diabetes status; use of metformin, sulfonylurea and antihypertensive medication; LCAT activity (A) or CETP mass (B); non-HDL cholesterol; and triglycerides." (PMID 30744100, 2019).
hypertriglyceridemia (43 papers, 2004 to 2025). A laboratory test result indicating elevated triglyceride concentration in the blood. "In addition, it has been suggested that hypertriglyceridemia and insulin resistance are linked through the cholesteryl ester transfer protein (CETP)." (PMID 34503545, 2021). "Besides CETP, the factors that associated with hypertriglyceridemia are also potential targets of preventing the changes in HDL component for the reason that hypertriglyceridemia is an initial requirement for the overproduction of TG-rich HDL." (PMID 21988829, 2011). "In hypertriglyceridemia, cholesteryl ester transfer protein is activated, promoting the exchange of TG and cholesteryl esters between very-low-density lipoproteins and LDL-C, leading to increased TG levels in LDL-C." (PMID 40070586, 2025). "Second, SHPΔhep mice were crossed with mice expressing the Cholesteryl Ester Transfer Protein (CETP) transgene, a genetic model of hypertriglyceridemia." (PMID 34065318, 2021). "Cholesteryl ester transfer protein in the presence of hypertriglyceridemia mediates the transfer of triglycerides from triglyceride-rich lipoproteins to HDL." (PMID 33142714, 2020). "This hypertriglyceridemia enhances the CETP mediated interchange of Tg from Tg-rich lipoproteins to HDL-L/HDL-VL and the subsequent Tg-enrichment of HDL-C." (PMID 30200612, 2018). "Actually, we have known that hypertriglyceridemia enhances the cholesteryl ester transfer protein (CETP)-mediated interchange of TG from TG-rich lipoproteins to HDL particles and the subsequent TG-enrichment of the HDL particle." (PMID 27563883, 2016). "Hypertriglyceridemia stimulates the enzymatic activity of cholesteryl ester transfer protein (CETP), which facilitates the transfer of TG from TG -rich lipoproteins to HDL and LDL in exchange for cholesteryl esters." (PMID 25471221, 2014). "Concurrent hypertriglyceridemia, another hallmark of GDM, further exacerbates HDL-C depletion through the cholesteryl ester transfer protein (CETP)-mediated exchange of lipids, leading to the formation of small, dense HDL-C particles with reduced anti-atherogenic capacity." (PMID 40731919, 2025). "Hypertriglyceridemia can activate cholesteryl ester transfer protein (CETP)." (PMID 39009987, 2024). "However, in conditions of hypertriglyceridemia and insulin resistance, the overstimulated cholesteryl-ester-transfer protein enriches HDL composition in TG by means of exchanging TG by cholesteryl esters with other lipoprotein subclasses." (PMID 36483472, 2022). "Therefore, the greater ability of CETP to transfer cholesterol esters in type 1 diabetic patients is probably related to mechanisms other than hypertriglyceridemia." (PMID 36471375, 2022). "In previous studies on hypertriglyceridemia patients, CETP activity was elevated." (PMID 34503545, 2021). "In addition, hypertriglyceridemia stimulates the enzymatic action of cholesteryl ester transfer protein which leads to an increase in triglyceride content of LDL and HDL." (PMID 30271452, 2018). "While these preliminary observations require additional experimentation, they do suggest that the efficacy of CETP inhibitors could be limited in the background of hypertriglyceridemia." (PMID 23801661, 2013). "Moreover, hypertriglyceridemia increases the activity of cholesteryl ester transfer protein (CETP)." (PMID 37940952, 2023). "Collectively, although the genetic variants of CETP might affect the efficacy of statins to reduce cardiovascular risk, and the variants of APOA5 may be associated with hypertriglyceridemia, further studies are needed to elucidate the exact meaning of the findings in this study." (PMID 35664336, 2022).
hypertriglyceridemia (continued). "In contrast, apoB is typically elevated in patients with moderate hypertriglyceridemia, because of the increased number of small dense LDL particles in these patients due to CETP-mediated lipid exchange and the subsequent increased lipolysis of LDL." (PMID 38331834, 2024). "In the setting of hypertriglyceridemia, excessive TGs are exchanged between TGs-rich LDL, large lbLDL and TRLPs through cholesteryl ester transfer protein (CETP) exchange, resulting in triglyceride-rich lipoprotein cholesterol (remnant cholesterol) increase." (PMID 37106374, 2023). "It is possible that in this transient hypertriglyceridemia, the HDL particles are TG-enriched via cholesteryl ester transfer protein mediated exchange with TG-rich lipoproteins." (PMID 15271218, 2004). "Hypertriglyceridemia will induce an increase in the exchange of cholesterol esters (CE) and triglycerides between VLDL, LDL and HDL via cholesteryl ester transfer protein (CETP)." (PMID 35216172, 2022). "Indeed, an overall defective RCT efficacy resulting from concomitant reduced efflux capacity and an elevated CETP activity have been reported in patients with familial hypercholesterolemia, type IIB hyperlipidemia or hypertriglyceridemia." (PMID 32466286, 2020). "However, this negative correlation between apoC1 levels and CETP activity was lost in CAD patients with hypertriglyceridemia or combined hyperlipidemia." (PMID 36471375, 2022). "The aim of this work was to examine the effect of the PPARα agonist, ciprofibrate, on the CETP gene expression, in the presence and absence of apolipoprotein (apo) CIII induced hypertriglyceridemia, and its impact on the HDL metabolism." (PMID 19930639, 2009). "While alcohol consumption does not produce favorable changes in hypertriglyceridemia, it may induce an increase in HDL levels by a mechanism that inhibits cholesteryl ester transfer protein (CETP) activity." (PMID 34372774, 2021). "Tx patients had moderate hypertriglyceridemia, hypercholesterolemia, and dyslipoproteinemia, disturbed triglyceride-rich lipoproteins (TRLs) and HDL composition, decreased LCAT, and slightly increased hsCRP but no CETP activity." (PMID 23479335, 2013). "The in vivo results of the present study show that Tx patients with and without statin therapy had moderate hypertriglyceridemia, hypercholesterolemia, dyslipoproteinemia, and atherogenic lipid and lipoprotein ratios, decreased LCAT mass, and slightly increased hsCRP, but no CETP activity." (PMID 23479335, 2013). "Thus, the aims of the present work were to examine the effect of ciprofibrate treatment on the CETP gene expression, in the presence and absence of apo CIII induced hypertriglyceridemia, and its impact on the HDL metabolism." (PMID 19930639, 2009).